TNF (tumor necrosis factor)
Diseases named in the same sentence as TNF in open-access papers (continued):
Sharing a sentence is not in itself a finding about the gene and the disease.
COVID-19 (continued). "Concerning the TNF role in COVID-19, a recent meta-analysis has highlighted a peculiar pro-inflammatory cytokine profile in patients with severe forms of the disease, and TNF-α was recognized as one of the prevailing cytokines during the COVID-19 cytokine storm." (PMID 36289890, 2022). "Similarly, Chen and co-authors reported the correlation between high concentrations of plasma IL-6 and TNFα and the severe course of COVID-19." (PMID 35213582, 2022). "When patients with severe ARDS from COVID-19 began to be studied it was reported early on that these patients were experiencing a “cytokine storm,” which included reports of many inflammatory cytokines, including IL-1 and TNF-α upregulated in the blood." (PMID 34723652, 2022). "However, data remain limited on the efficacy and the safety of anti-TNFα treatment in patients with COVID-19, based on large-scale clinical trials." (PMID 36417106, 2022). "In the third phase of COVID-19, over-production of pro-inflammatory cytokines including TNF-α is very common and this, together with other immune system dysregulations, is considered the main cause of the worsening of the clinical course and the increased risk of admission to the ICU and death." (PMID 35812420, 2022). "A number of studies have shown that the sign of COVID-19 was the cytokine storm with elevated levels of interleukin-6 (IL-6), IL-1β, complement C1r (C1R), tumor necrosis factor-alpha (TNF-α), chemokine (C-C-motif) ligand 2 (CCL2), and granulocyte-macrophage colony-stimulating factor (GM-CSF)." (PMID 35726234, 2022). "In COVID-19 patients with acute respiratory distress syndrome (ARDS), ATII increases NOX and causes vasoconstriction and thrombosis via ROS, IL-6, tumour necrosis factor-Alpha (TNF-α), and other cytokines." (PMID 35639261, 2022). "Indicative cytokines in severely ill COVID-19 patients are characterized by boosted expression of IL-6, TNF-α, IL-17 macrophage inflammatory proteins 1-α (MIP-1α), MCP3, GM-CSF, IL-2, and IP-10, in addition to the elevated chemokines (IP-10, CCL2/MCP1, CXCL1, CXCL5)." (PMID 36081516, 2022). "SSRIs may help COVID-19 patients to prevent cytokine release syndrome responsible for complicating illness progression and increasing TNFα." (PMID 36532776, 2022). "Interestingly, others suggested a potential disease-driving role of IFN-γ in combination with TNF, possibly inducing inflammatory cell death during severe COVID-19 via PANoptosis." (PMID 36129445, 2022). "However, interestingly, there is some evidence that patients on anti-TNF therapy are less likely to experience severe COVID-19." (PMID 35893815, 2022). "Finally, COVID-19 asymptomatic subjects treated with anti-TNF-α had a trend to higher effector CD8+, memory, and class-switched B cells than the symptomatic ones, while TH1 cells were comparable in the two groups." (PMID 35757699, 2022). "The results of network pharmacology analysis showed that Yinqiao powder may inhibit inflammatory responses by suppressing IL-6, CXCL2, TNFα, NF-κB, etc., in the treatment of COVID-19." (PMID 36467981, 2022). "Furthermore, TNF induced the production of IL-6 and other cytokines, involved in the process of CS in COVID-19." (PMID 35350754, 2022). "Interestingly, our study shows that post-COVID-19 individuals are characterized by dysregulation of mediators of the tumor necrosis factor-α (TNFα) pathway and consistent upregulation of matrix metalloproteinases (MMPs)." (PMID 36405747, 2022). "Retrospectively, we evaluated whether there was a difference in the frequency and severity of COVID-19 in our patients diagnosed with ankylosing spondylitis (AS), 77 of whom were using anti-TNF and 49 of whom didn’t use anti-TNF." (PMID 36161620, 2022). "IL-17, TNF, and the MAPK signaling pathway have previously been implicated in enabling thrombosis, a frequent complication in COVID-19 ARDS as well as non-COVID-19 ARDS." (PMID 36121875, 2022).
COVID-19 (continued). "Limiting CRS is especially important for COVID-19 patients, who often display a cytokine storm even in the absence of such therapies, with increased levels of inflammatory cytokines and chemokines (TNF-α, IL-1, IL-6, IL-8, IL-10, IL-18, and MCP-1) that severely damage pulmonary tissue." (PMID 35546150, 2022). "Moreover, elevated levels of cytokines IL-6, IL-10, and TNF-α were observed in severe COVID-19 patients, directly affecting T-cell subsets and indirectly affecting dendritic cells and neutrophils, thereby reducing lymphocyte count." (PMID 35615369, 2022). "In parallel, TNF is present in excess amounts in blood and diseased tissues of COVID-19 patients." (PMID 35992513, 2022). "There is also a clear association between others such as IP-10, MCP-1, MIP-1α, TNF-α and IL-6 and COVID-19 severity when comparing ICU-patients with non-ICU patients." (PMID 36466830, 2022). "In addition, monocytes in severe cases display an increase of the type I IFN inflammatory genes combined with the reduction of the IFNα levels and elevated levels for a large number of cytokines (IL-10, IL-6, IL-11, TNF) for severe of COVID-19 cases." (PMID 36230912, 2022). "Furthermore, TNF-α expression was significantly higher in the severe and moderate COVID-19 groups than in controls (P<0.001), and this increase was less than tenfold higher than in controls." (PMID 35982898, 2022). "TNF-α showed a higher immunoreactivity in the COVID-19 group than in the control group (p < 0.01)." (PMID 34463916, 2022). "In addition, high blood levels of IL-1β, IL-2, IL-8, IL-17, G-CSF, GMCSF, IP-10, MCP-1, and TNF-α are indicative for severe COVID-19." (PMID 35883640, 2022). "We included in our tests a set of cytokines and chemokines with serum concentrations that were shown to increase during COVID-19, and this increase might also be reflected in breastmilk: TNF-α, IL-6, IFN-β, IL-1β, IFN-γ, IL-2, GM-CSF and IL-5, IP-10." (PMID 36560410, 2022). "It is a possibility that the type I IFNs might be contributing to the hyper inflammation responses by intensifying the inflammation driven by TNF/IL-1β in the severe progression of COVID-19." (PMID 36415655, 2022). "In addition, it was also found that the plasma levels of IL2, IL7, IL10, IL-6, TNFα, and e lymphopenia were higher in patients with COVID-19." (PMID 35295802, 2022). "The main finding regarding medications was that the use of thiopurines, with or without anti-TNF therapy, was associated with a fourfold higher risk of developing severe COVID-19 outcome (hospitalization and/or death) than using anti-TNF therapy alone." (PMID 34755038, 2021). "Reproducible immune correlates of severe COVID-19 include prolonged detection of proinflammatory cytokines such as IL-6, TNFα, and IL-8, diminished type I and type III interferon, and marked lymphopenia, as well as mixed evidence for immune exhaustion and dysfunctional myeloid populations." (PMID 34352228, 2021). "In COVID-19 patients, increased plasma pro-inflammatory cytokines such as IL-1, IL-6, IL-8, and TNF-α levels have been reported that may contribute to CRS onset in severe COVID-19 patients." (PMID 34176095, 2021). "In comparison with other pulmonary infections, severe COVID-19 is characterized by massive activation of the inflammatory response, which is substantiated in the so-called “cytokine storm” with elevation of IL-6 and TNF-α in blood." (PMID 34326704, 2021). "Based on recently published immunological data, COVID-19 patients have a dysregulated immune response, characterized by the release of multiple inflammatory cytokines, such as tumor necrosis factor (TNF), interleukins, as well as a decreased number of T cells, B cells, and natural killer (NK) cells." (PMID 33757410, 2021).
COVID-19 (continued). "In the early phases of COVID-19, the proinflammatory response often predominates, with the massive production of proinflammatory cytokines such as tumor necrosis factor (TNF)-a, IL-8 and IL-6 that stimulate the effector functions of neutrophils, macrophages and Th1 cells." (PMID 34441796, 2021). "Furthermore, this information is relevant in order to study the possibility of establishing anti-TNF therapy in COVID-19 patients." (PMID 34445140, 2021). "TNF-α-induced ROS production could also contribute to the spread of COVID-19 symptoms to distant tissues such as the brain." (PMID 34204362, 2021). "Severe COVID-19 is involved in the inflammatory cytokine storm and inflammatory events, such as increased proinflammatory cytokine levels, including tumor necrosis factor-α (TNF-α), interleukin 1 (IL-1), interferon-γ inducible protein 10 (IP-10), and IL-6." (PMID 34199223, 2021). "Furthermore, we used the IL-2R/IL-6 and TNF-α/IL-6 ratios on behalf of the Th1/Th2 ratios to determine which type of T-helper cells was dominant in the progression of COVID-19." (PMID 33776910, 2021). "Depression and COVID-19 demonstrate shared patterns of immunological function, especially around a pro-inflammatory state characterized by elevation in cytokines including IL-6, TNFα, and IL-1β." (PMID 33967944, 2021). "Indeed, increased levels of IL-17 and TNF-α have been found in the blood (serum) of individuals with COVID-19 (especially in those who need intensive care)." (PMID 34177297, 2021). "Elevated serum cytokines, including interleukin-6 (IL-6), IL-10, tumor necrosis factor-α (TNF-α) and interferon-γ, may cause fatal ARDS and coagulation disorders in COVID-19 patients." (PMID 34001244, 2021). "In fact, drugs targeting TNFα or IL-1 and 6 might have a beneficial effect, as these cytokines are involved in COVID-19 pathogenesis." (PMID 34177927, 2021). "Furthermore, the involvement of C5a in the inflammatory process of COVID-19 is supported by identifing in patients with COVID-19, increased monocyte production of inflammatory cytokines, such as IL-6, TNF-α, and CCL2." (PMID 33669011, 2021). "Given such an immune system imbalance, patients with thyroid autoimmune diseases might undergo a worse clinical course of COVID-19 due to higher baseline levels of serum IL-6 and TNF alpha compared to healthy individuals." (PMID 33765288, 2021). "In addition, from the analysis of cytokines in our patients we identified a subgroup, called COVID-plus, including COVID-19-positive patients who presented much higher levels of IL-6, TNF-α, IL-1β, and CD25 than other groups." (PMID 34578450, 2021). "Evidence has shown a potential association of MCs with COVID-19, and the activation of MCs located in the submucosa of the respiratory tract by SARS-CoV-2 is known to lead to the release of pro-inflammatory cytokines such as IL-1, IL-6 and TNF-α." (PMID 34359931, 2021). "Taken together, TNFα along circulating cytokines may contribute to COVID-19 thrombotic complications." (PMID 34326843, 2021). "Importantly, the levels of TNF- α, IL-2R, IL-6, IL-8, and IL-10 were significantly correlated with survival time of cancer patients with COVID-19." (PMID 33735106, 2021). "However, its decrease in COVID-19 patients significantly increases the secretion of pro-inflammatory factors such as IL-6, TNF-α, MCP-1, and IL-1 β, and decreases the secretion of IL-10 and transforming growth factor-β (TGF-β)." (PMID 35062245, 2021). "Levels of cytokines can explain some of the COVID-19 complications, such as septic shock and multiorgan failure due to TNF-α increase; moreover, cytokine storm is also found in older patients and those with comorbidities, which are considered risk factors for the disease complication." (PMID 33868239, 2021). "This would be in line with increased expression of pro-inflammatory cytokines such as IFN-γ or TNF-α in severe courses of COVID-19, as both cytokines may affect erythropoiesis or erythrocyte half-life." (PMID 34677368, 2021).
COVID-19 (continued). "BCG could have associated with the trained immunity process through manipulating epigenetics of immune cells to produce inflammatory cytokines such as IL-1, IL-6, and TNF to provide a beneficial effect against COVID-19." (PMID 34512561, 2021). "For example, Tocilizumab and anti-TNF may play a role in the dampening of the hyperinflammatory state which characterizes most severe forms of COVID-19." (PMID 34572185, 2021). "Clinically, targeting IL-1β, IL-6, and TNF-α have gained some success in severe COVID-19 patients." (PMID 34150848, 2021). "Moreover, plasma levels of IL-6, IL-8, and TNF-α peaked before death as demonstrated in autopsies of COVID-19 patients." (PMID 34367380, 2021). "Another study showed that Shufeng Jiedu prescription may prevent COVID-19 through its active ingredients likely quercetin, luteolin, wogonin, and kaempferol by targeting TNF, IL-10, IL-2, IL-6, STAT1, and CCL-2." (PMID 34861881, 2021). "Furthermore, immunomodulation at the level of NF-kB activation and the inhibition of IkB degradation along with TNF-α inhibition will potentially result in a reduction in the cytokine storm and alleviate the severity of COVID-19." (PMID 34824310, 2021). "Dramatically, over 50% of COVID-19 patients needed respiratory support due to an excessive pro-inflammatory response, with a massive release of interleukins (IL)-1β, IL-6 and Tumor Necrosis Factor (TNF)-α, chemokines and anti-inflammatory cytokines." (PMID 33815368, 2021). "The long-term systemic corticosteroid (especially prednisone > 20 mg/day), sulfasalazine/mesalamine and thiopurine usage is associated with an increased risk of severe COVID-19, whereas tumor necrosis factor (TNF) antagonist therapy is not." (PMID 34708016, 2021). "Besides IL-6, SARS-CoV-2 infection leads to the secretion of high amounts of IL-1β, IL-2, IL-4, IL-7, IL-10, monocyte chemoattractant protein (MCP)-1, and tumor necrosis factor (TNF)-α into the plasma of COVID-19 patients." (PMID 34122407, 2021). "A TNF inhibitor suppresses inflammation and also reduces D-dimer level and pro-thrombin fragments; therefore, a TNF inhibitor may also attenuate COVID-19-induced thrombosis." (PMID 34959657, 2021). "COVID-19 patients with T2D also demonstrate increased likelihood of a cytokine storm compared to nondiabetics, with a recent study showed elevated serum IL-8 and TNFα levels in these patients, although the mechanisms responsible for this are unclear." (PMID 34479991, 2021). "To further investigate the effect of SARS-CoV-2 infection on MAIT cell function, we quantified the frequencies of MAIT cells expressing cytokines (IFN-γ and TNF-α) and cytolytic molecules (granzyme B and perforin) in 8 uninfected individuals and 7 COVID-19 patients." (PMID 34238985, 2021). "Studies have shown that compared with that of mild cases, plasma levels of IL2, IL6, IL7, IL10, G-SCF, IP10, MCP1, ferritin, and TNFα in severe cases of COVID-19 were elevated, indicating that the participation of these cytokines contributes to the pathogenesis of deterioration." (PMID 34305916, 2021). "In addition, TNF was present in the blood and disease tissues of patients with COVID-19, which is important in nearly all acute inflammatory reactions, acting as an amplifier of inflammation." (PMID 34580601, 2021). "In COVID-19, serum concentrations of proinflammatory cytokines, including IL-2, IL-6, and tumor necrosis factor (TNF)-a, were markedly increased in severe cases than moderate cases, suggesting that cytokine storms could be associated with disease severity." (PMID 34903765, 2021). "In addition, it has become clear that abrupt release of IL-1β and TNF-α also contributes significantly to the severity of COVID-19 pathogenesis." (PMID 33959020, 2021).
COVID-19 (continued). "Tumor necrosis factor-α (TNF-α) and interleukin 6 (IL-6) production by circulating monocytes is sustained in severe COVID-19 patients but not in bacterial sepsis or influenza-associated cytokine storms in which the monocyte numbers and function are impaired." (PMID 33672738, 2021). "The increase in TNF-α occurs in individuals with severe forms of COVID-19." (PMID 33008960, 2021). "The authors propose that serum IL-6 and tumor necrosis factor-alpha (TNF-α) levels should be considered in the management and treatment of patients with COVID-19 to stratify prospective clinical trials, guide resource allocation, and inform therapeutic options." (PMID 33747583, 2021). "Given the significant dysregulation of key cytokines, such as IL-6 and TNF-α, in patients with COVID-19, we analyzed the RNA-Seq data from these in vitro infection models and compared the data with samples from patients with COVID-19 for similar immune gene expression signatures." (PMID 34731091, 2021). "Another study also reported that type I IFN responses were highly impaired in the peripheral blood of patients with severe or critical COVID-19, as indicated by low levels of type I IFNs and ISGs, despite increased levels of TNF-, IL-6-, and NFκB-driven inflammatory responses." (PMID 33953323, 2021). "IL-6 and TNFα were significantly elevated in COVID-19 patients, which might result in low LDL-C level." (PMID 34504873, 2021). "Additionally, the anti-inflammatory activity, promoted by MSCs in COVID-19 patients, it was demonstrated by a decreased level of TNF-α, and a concurrent elevation in the concentration of the IL-10." (PMID 33815867, 2021). "Likewise, in severe patients, the possible slight promotion of NETs by TNF-α can drive the hazardous results observed in COVID-19 patients." (PMID 34603282, 2021). "A series of correspondences published in the Annals of Rheumatic Diseases discussed the role of corticosteroid modification in the treatment of patients with sarcoidosis who developed COVID-19 and later highlighted potential protective qualities of TNF-alpha antagonists." (PMID 34336892, 2021). "Indeed, elevated levels of CCL2, CXCL10, IL-6 and TNFα have been identified in severe COVID-19 patients compared to patients with a mild form of the disease." (PMID 34452468, 2021). "We then analyzed three major inflammatory cytokines reportedly associated and possibly causally involved in COVID-19 pathology irrespective of outcome, namely IL-6, IL-8 and TNF." (PMID 34943881, 2021). "In parallel, a critical reduction of IL-1β, IL-1RA, IL-6, and TNF-α concentration was evident 2 days after MSC infusion, mimicking the effectiveness of other immunomodulatory agents, such as baricitinib, in dampening COVID-19-associated inflammation." (PMID 34078447, 2021). "One of the key contributing factors for the higher mortality and morbidity in COVID-19 patients is excess local production of pro-inflammatory cytokines, such as IL-1β, IL-6, IL-8 and TNF in key organs (heart, lungs and liver), which is termed a cytokine storm." (PMID 34422917, 2021). "Laboratory abnormalities of most affected COVID-19 patients include neutrophilia, lymphopenia, increased C- reactive protein, and pro-inflammatory cytokines such as interleukin 6 (IL-6), IL-2, IL-7 and tumor necrosis factor-alpha (TNFα) among others." (PMID 34072088, 2021). "This suggests that antibodies that target IL-6 and TNF-signaling may restore NK cell functions in COVID-19 patients." (PMID 34578460, 2021). "Treatment with b/tsDMARDs TNF-inhibitors or tocilizumab may have a clinical benefit in reducing COVID-19 related hospitalization or mortality." (PMID 34490312, 2021). "Increased serum levels of proinflammatory cytokines (TNF-α, IL-1, and IL-6) and chemokines (IL-8) have been found in patients with severe COVID-19, compared with individuals with mild disease, suggesting a possible role for a hyperinflammatory response in the pathogenesis of COVID-191,2." (PMID 34728719, 2021).